CISD2 (CDGSH iron sulfur domain 2)
Description:
Regulator of autophagy that contributes to antagonize BECN1-mediated cellular autophagy at the endoplasmic reticulum. Participates in the interaction of BCL2 with BECN1 and is required for BCL2-mediated depression of endoplasmic reticulum Ca(2+) stores during autophagy. Contributes to BIK-initiated autophagy, while it is not involved in BIK-dependent activation of caspases. Involved in life span control, probably via its function as regulator of autophagy.
Synonyms: Miner1; NAF-1; ERIS; ZCD2; WFS2
Tractability: Small molecule: a structure with a bound ligand is known. Antibody: UniProt predicts a signal peptide or a membrane-spanning region. PROTAC: ubiquitination databases record sites on it; its protein half-life has been measured; a small molecule that binds it is known.
Gene: Protein-coding gene on chromosome 4 (102,868,971 to 102,892,807, forward strand). Ensembl gene ENSG00000145354.
Subcellular location: Endoplasmic reticulum membrane; Mitochondrion outer membrane
Subcellular location (Human Protein Atlas): Endoplasmic reticulum
Gene Ontology:
Molecular function: 2 iron, 2 sulfur cluster binding; protein binding; protein homodimerization activity; RNA binding
Biological process: regulation of autophagy; autophagy of mitochondrion
Cellular component: endoplasmic reticulum; endoplasmic reticulum membrane; membrane; perinuclear endoplasmic reticulum; protein-containing complex; mitochondrial outer membrane; cytoplasm
Genetic constraint (gnomAD): Loss-of-function variants: 1 observed, 10.85 expected, observed/expected ratio (o/e) 0.0922, 90% interval 0.032 to 0.44. The upper end of that interval is the gene's LOEUF score, 0.44, which puts it in group 1 of 6, group 1 being the genes least tolerant of losing a copy. Missense variants: 94 observed, 136.38 expected, observed/expected ratio (o/e) 0.69, 90% interval 0.58 to 0.82. Synonymous variants: 48 observed, 48.92 expected, observed/expected ratio (o/e) 0.98, 90% interval 0.78 to 1.25.
Gene-disease validity (ClinGen):
ClinGen rates the evidence that CISD2 causes each of these diseases.
Wolfram syndrome (autosomal recessive): Definitive. Wolfram syndrome (WS) also known as DIDMOAD, is a neurodegenerative disorder characterized by type I diabetes mellitus (DM), diabetes insipidus (DI), sensorineural deafness (D), bilateral optical atrophy (OA) and neurological signs.
Homologues: Orthologues: dog CISD2 (99% identical), rabbit CISD2 (99% identical), macaque CISD2 (99% identical), pig CISD2 (99% identical), guinea pig CISD2 (98% identical), mouse Cisd2 (96% identical), rat Cisd2 (94% identical), zebrafish cisd2 (80% identical), chimpanzee CISD2 (76% identical), tropical clawed frog CISD2 (74% identical), Drosophila melanogaster Cisd2 (43% identical), Caenorhabditis elegans cisd-1 (36% identical). Paralogues in human: CISD1 (43% identical), CISD3 (22% identical).
Diseases named in the same sentence as CISD2 in open-access papers:
CISD2 is named in the same sentence as 94 diseases in open-access papers, as found by Europe PMC text mining. Sharing a sentence is not in itself a finding about the gene and the disease. The quoted sentences say what the papers report.
Wolfram syndrome (37 papers, 2013 to 2025). "Patients with a similar disease named Wolfram syndrome 2 also appear with DM, hearing loss, and optic atrophy but the genetic cause is different, involving mutations in the CISD2 gene." (PMID 39408828, 2024). "Wolfram syndrome is a neurodegenerative disorder caused by pathogenic variants in the genes WFS1 or CISD2." (PMID 37508961, 2023). "A homozygous mutation of the CISD2 gene was identified in three related families of patients with Wolfram syndrome 2 (WFS2; MIM 604928)." (PMID 36430496, 2022). "Wolfram syndrome caused by the CISD2 gene mutation exhibits very different clinical features, characterized by peptic ulcer disease, bleeding tendencies secondary to abnormal platelet aggregation and absence of enuresis." (PMID 34404380, 2021). "Recessive mutations in the CISD2 gene coding for CISD2 are the causative factor for Wolfram syndrome 2 (or WFS2), a rare autosomal recessive neurodegenerative disorder leading to severe neurological disabilities and a drastic decrease in life span." (PMID 33916457, 2021). "Among these 26 papers, five patients had wolfram syndrome caused by mutations in the CISD2 gene, while the rest had disease caused by mutations at different nucleotide sites in exons 4, 5 and 8 of the WFS1 gene." (PMID 34404380, 2021). "All papers are case reports on single nucleotide polymorphisms on the WFS1 and CISD2 genes in wolfram syndrome." (PMID 34404380, 2021). "Regarding Wolfram syndrome 2, the CISD2 gene encodes a highly conserved zinc finger Fe–S cluster containing a protein called CISD2 or Miner1." (PMID 34992533, 2021). "Examples include CISD2, a causal gene for Wolfram syndrome which manifests with early-onset diabetes and ABAT, which encodes Gamma-aminobutyric acid transaminase (GABA-T)." (PMID 34456865, 2021). "Wolfram syndrome is a rare multisystem disorder caused by mutations in WFS1 or CISD2 genes leading to brain structural abnormalities and neurological symptoms." (PMID 31796109, 2019). "A small number of Wolfram syndrome patients have Wolfram syndrome type 2, which is caused by mutations in the CISD2 gene." (PMID 31366393, 2019). "In humans, mutations in CISD2 result in Wolfram syndrome 2, a disease in which the patients display juvenile diabetes, neuropsychiatric disorders and defective platelet aggregation." (PMID 29666474, 2019). "Wolfram syndrome 2 is caused by mutations in WFS2 (also called CISD2), which encodes for Miner1 (also named ERIS), an iron-sulfur cluster-containing protein localized in mitochondria-associated ER membranes and mitochondria." (PMID 28951826, 2017). "Mutations of human CISD2 cause Wolfram syndrome 2, a neurodegenerative disease associated with diabetes mellitus, optic atrophy and a decreased lifespan (OMIM 222300)." (PMID 29084988, 2017). "Wolfram syndrome is a rare genetic disease caused by mutations in the WFS1 or CISD2 gene." (PMID 39034309, 2024). "Wolfram syndrome 2 is caused by mutations in the CISD2 gene." (PMID 34992533, 2021). "Moreover, the participation of MAMs in relation to another subtype of Wolfram syndrome with mutations in the CISD2 gene—the WFS2 syndrome—was also proved." (PMID 34801048, 2021). "Importantly, CISD2 is the causative gene for Wolfram syndrome 2 (WFS2; MIM 604928)." (PMID 31593566, 2019). "Transcriptional splicing error of CISD2 in mice leads to breakdown and dysfunction of mitochondria, which is an causative of the neurological genetic disorder Wolfram Syndrome (WFS)." (PMID 27007153, 2016). "Wolfram Syndrome (WFS) is a rare, neurodegenerative disorder caused by mutations in the WFS1 or CISD2 genes, leading to severe multi-organ dysfunction, including diabetes, optic atrophy, and hearing loss." (PMID 41235102, 2025). "This is also well substantiated in the case of Wolfram syndrome, where diabetes is a core element of its phenotype, caused by mutations in the WFS1 or CISD2 genes." (PMID 41234236, 2025).
Wolfram syndrome (continued). "In Wolfram syndrome, mutations in WFS1 or CISD2 disrupt ER Ca2+ handling, impairing IP3R-mediated Ca2+ transfer to mitochondria." (PMID 41415579, 2025). "Using exome sequence data from individual V:3, candidate variants obtained from filtering as well as Wolfram syndrome genes WFS1 and CISD2 were evaluated via the Integrative Genomics Viewer (IGV)." (PMID 33879837, 2021). "Two genetically distinct variants have been identified, type-1 and type-2 Wolfram syndrome, which result from mutations in the WFS1 and CISD2, respectively." (PMID 31796109, 2019). "The pathogenesis of Wolfram syndrome is attributed to genetic mutations in two genetic loci on chromosome 4 (WFS1 and CISD2- also known as ZCD2 gene or WFS2 gene)." (PMID 31796109, 2019). "Strikingly, there is a ~70% decrease in Cisd2 protein, a key regulator of lifespan in mice and the disease gene for Wolfram syndrome 2 in humans, within the gastrocnemius after middle age among mice." (PMID 29168286, 2018). "Wolfram syndrome, caused by WFS1 or CISD2 gene mutations, disrupts ER Ca2+ regulation in neurons." (PMID 39034309, 2024). "Wolfram syndrome (WS) is a rare genetic disease caused by mutations in the wolframin gene (WFS1), resulting in the more prevalent type I WS, or in the CDGSH iron-sulfur-containing domain 2 gene (CISD2), resulting in the rarer type II WS1,2." (PMID 39034309, 2024). "We systematically identified all potentially relevant articles from PubMed and Web of Science, Search terms about “Wolfram syndrome” and “WFS1” and “CISD2” and “gene mutation sites”, were used in various combinations and permutations across the databases.There were a total of 26 papers." (PMID 34404380, 2021). "Despite the exact mechanism not being known, preclinical experiments in several Wolfram syndrome 2 cases showed that CISD2 deficiency leads to neuronal and β-cell death, a process probably mediated by calpain activation." (PMID 34992533, 2021). "Wolfram Syndrome has been linked to mutations in both WFS1 and CISD2 (Miner1)." (PMID 23703906, 2013). "Similarly, Wolfram syndrome is a constellation of diabetes insipidus, diabetes mellitus, optic atrophy and deafness (DIDMOAD) that can be observed with pathological variants in the autosomal WFS1 and CISD2 genes." (PMID 38397177, 2024). "Although not as common as WFS1, mutations in WFS2 or CISD2 gene also cause Wolfram Syndrome." (PMID 34360909, 2021). "Wolfram syndrome (WFS) is a rare autosomal recessive genetic disease whose main cause is mutations in the WFS1 and CISD2 genes." (PMID 34404380, 2021). "Wolfram syndrome is considered a prototype ER disorder, as both WFS1 and CISD2 proteins localize to the ER and are crucial for maintaining ER homeostasis." (PMID 41234236, 2025). "Individuals with Wolfram syndrome typically present with one or more of the main DIDMOAD symptoms, and diagnosis is confirmed by genetic testing of the WFS1 gene; the CISD2 mutation is not commonly screened for." (PMID 31366393, 2019). "Known Wolfram syndrome genes WFS1 and CISD2 did not lie within the regions of homozygosity." (PMID 33879837, 2021).
Wolfram syndrome 2 (25 papers, 2014 to 2025). Any Wolfram syndrome in which the cause of the disease is a mutation in the CISD2 gene. "Apart from WFS1, mutations in another MAM-resident protein CISD2 associated with Wolfram syndrome type 2 caused mitochondrial abnormalities in mouse models of Cisd2 deficiency." (PMID 37163979, 2023). "Two types of WS are characterized so far and Wolfram syndrome type 2 is due to mutation in CISD2, a protein mostly expressed in MAMs." (PMID 29511163, 2018). "Type 2 Wolfram syndrome, caused by mutations of the CISD2 gene on the chromosome 4q22, has been diagnosed in three large Jordanian families." (PMID 25255707, 2014). "A genetically and clinically distinct form, Wolfram syndrome type 2 (WFS2), is caused by pathogenic variants in the CISD2 gene." (PMID 41323015, 2025). "The majority of patients harbour pathogenic WFS1 mutations, but recessive mutations in a second gene, CISD2 (CDGSH iron-sulfur domain-containing protein 2), have been described in a few patients with Wolfram syndrome type 2 (WFS2, OMIM #604928)." (PMID 28335035, 2017). "The majority of patients harbour pathogenic WFS1 mutations, but recessive mutations in a second gene, CISD2, have been described in a small number of families with Wolfram syndrome type 2 (WFS2)." (PMID 28335035, 2017). "CISD2, responsible for Wolfram Syndrome type 2 (WS2), encodes the endoplasmic reticulum intermembrane small protein (ERIS), a small intermembrane protein which plays an important role in ER, mitochondria membrane integrity, and in the functional cross-talk between these two cellular compartments." (PMID 35270448, 2022). "A partial overlapping disease, Wolfram syndrome type 2 (WS2), is caused by recessive mutations in the CDGSH Iron Sulfur Domain 2 (CISD2) gene, encoding for a MAM localized protein (also known as Miner1 or ERIS) that, similarly to WFS1, regulates the UPR and calcium homeostasis." (PMID 33806088, 2021). "Wolfram syndrome type 2 (WS2, OMIM #604928) is a disorder caused by mutations in the CISD2 gene." (PMID 29511163, 2018).
diabetes mellitus (16 papers, 2013 to 2026). A metabolic disorder characterized by abnormally high blood sugar levels due to diminished production of insulin or insulin resistance/desensitization. "As a well-studied member of the NEET family, CISD2 has been linked to diseases like diabetes, obesity, aging, and neurodegeneration, and is increasingly recognized as a potential cancer treatment target." (PMID 40421419, 2025). "With these results, we propose our CISD2 peptide as a new therapeutic tool that successfully restores IP3R activity to effectively ameliorate the diabetic complications associated with WS." (PMID 40181095, 2025). "CISD2 is primarily known to cause the neurodegenerative Wolfram syndrome 2 (WFS2) through a transcriptional splicing error, leading to hearing deficiency, blindness, diabetes mellitus, and a reduced life expectancy." (PMID 34946818, 2021). "To confirm that our WT CISD2 peptide can rescue diabetes-like phenotypes of dWFS1 and dCISD mutant flies, we generated transgenic flies expressing the analogous dCISD peptide." (PMID 40181095, 2025). "Differentiating WFS1 (wolframin mutation), usually presenting with diabetes mellitus and optic atrophy, from WFS2 (CISD2 mutation), often associated with additional gastrointestinal ulceration and bleeding, remains important in guiding counseling and prognosis." (PMID 41321884, 2025). "WS2, a rarer manifestation that has been linked to recessive CISD2 mutations, shares many clinical features with WS1 including diabetes mellitus, but distinctively presents with gastrointestinal complications like peptic ulcers and bleeding tendencies without diabetes insipidus." (PMID 40181095, 2025). "Notably, we identified a CISD2 peptide that alleviates ER calcium defects of WFS1- or CISD2-deficient cells by solely increasing IP3R activity, further showing that this peptide mitigates diabetes-like phenotypes as well." (PMID 40181095, 2025). "Mutations in the gene that encodes CDGSH iron sulfur domain 2 (CISD2) are causative of Wolfram syndrome type 2 (WFS2), a rare autosomal recessive neurodegenerative disorder mainly characterized by diabetes mellitus, optic atrophy, peptic ulcer bleeding and defective platelet aggregation." (PMID 29237418, 2017). "CISD2 is expressed in multiple tissues, including the pancreas and heart, which may explain the combination of patent ductus arteriosus, small-for-gestational-age status, and diabetes in this patient." (PMID 41498801, 2026). "Additionally, a second gene, CISD2, located on chromosome 4q22, has been identified in individuals with WFS type 2 (WFS2), which leads to early onset optic atrophy, diabetes mellitus, deafness, bleeding tendency and upper intestinal ulcers, a shortened lifespan, but notably not diabetes insipidus." (PMID 39527371, 2025). "Lastly, our study identified a short CISD2 peptide of 18 amino acids, and the respective dCISD peptide in flies, that effectively binds to and activates IP3R to ameliorate diabetes-like symptoms, presenting a novel therapeutic method to treat WS." (PMID 40181095, 2025). "These experiments suggest that WFS1 and CISD2 interact independently at distinct sites on IP3R to manipulate its activity, demonstrating their roles as IP3R regulators and emphasizing ER calcium dysfunction as a major mechanism of WS-related diabetes." (PMID 40181095, 2025).
breast carcinoma (11 papers, 2016 to 2025). "CISD2 mutations can lead to the loss of [2Fe-2S] cluster function, reducing tumor size and resulting in iron and ROS accumulation in breast cancer cells." (PMID 39605902, 2024). "Although CISD2 activity is essential for normal development, overexpression of CISD2 has been implicated in several types of human malignancies, including gastric cancer, breast cancer, and hepatocellular carcinoma, indicating that it plays an oncogenic role." (PMID 35493303, 2022). "Silencing CISD1 and CISD2 or targeting breast cancer mitochondria with the mitogen derivative MAD-28 can destabilize iron-sulfur proteins, elevate mitochondrial iron accumulation, and hinder breast cancer cell growth." (PMID 39867656, 2024). "The recently identified iron-sulfur proteins CISD1 and CISD2 facilitate the proliferation of breast cancer cells." (PMID 39867656, 2024). "CISD2 is also involved in the development and progression of multiple cancer types, including breast cancer, lung cancer, and colorectal cancer." (PMID 38155967, 2023). "Previously we showed that breast cancer cell lines with suppressed NAF-1/CISD2 expression (grown in culture or xenograft tumors) display features of activated apoptosis." (PMID 29666474, 2019). "CISD2 was shown to be elevated in human epithelial breast cancer cells and to reduce cell proliferation and tumor growth significantly." (PMID 26565812, 2016). "Inhibition of CISD2 has been shown to significantly induce the accumulation of iron and production of ROS in the mitochondria of breast cancer cells, suggesting that CISD2 plays a crucial role in maintaining iron homeostasis and facilitating iron-cluster transfer within mitochondria." (PMID 39605902, 2024). "Similarly, Knocking down CISD2 expression significantly increases iron levels in breast cancer cells and promotes iron uptake, leading to autophagy activation." (PMID 39605902, 2024). "Moreover, CISD2 was found to be upregulated in breast cancer and early-stage cervical cancer, suggesting that it has an important role in cancers." (PMID 26565812, 2016). "The CISD2 (NAF-1, nutrient-deprivation autophagy factor-1) protein is reported to regulate TXNIP expression through a process that involves the perturbation of mitochondrial labile iron, mitochondrial ROS and triggered ferroptosis in breast cancer cells." (PMID 37794178, 2023).
optic atrophy (10 papers, 2017 to 2025). A disorder characterized by loss of optic nerve fibers. "CISD2 mutations are involved in WFS2, which is characterized by DM, optic atrophy, and deafness with an absence of diabetes insipidus and psychiatric disorders." (PMID 33946243, 2021).